YOD1 (YOD1 deubiquitinase)
Diseases named in the same sentence as YOD1 in open-access papers (continued):
Sharing a sentence is not in itself a finding about the gene and the disease.
tumor (continued). "To further verify the expression of YOD1 gene, we downloaded and analyzed five data sets from the GEO database: GSE15471, GSE16515, GSE28735, GSE71729, and GSE62165 included 278 tumor samples and 186 normal tissues." (PMID 35642058, 2022). "Both YOD1 and ZNF24 exhibited low expression in the majority of the tumor specimens." (PMID 40274778, 2025). "Manipulation of YOD1 expression was assessed in vitro and in vivo for TNBC cell proliferation, migration, invasion, cell-cycle and drug resistance, using colony formation assay, transwell assay, CCK8 assay, TUNEL assay, flow cytometric analysis and xenograft tumor assay." (PMID 37667382, 2023). "In the tumor bearing livers, the methylation of Derl3, Herp, and Yod1 was reduced in the tumor portion compared to the normal liver portion whereas the methylation of Creld2 or Wfs was not significantly changed in the tumor portion compared to the liver portion." (PMID 24198826, 2013). "Particularly, the methylation of Derl3 and Herp was reduced in the tumor portion of older KOs, methylation of Creld2, Wfs, and Yod1 was not changed in the normal liver portion, and mRNA expression of Hrd1 and Yod1 was remarkably increased in both liver and tumor portions of KO with liver tumors." (PMID 24198826, 2013). "In addition, the methylation of Derl3, Herp and Yod1 was increased in the normal liver portion of tumor bearing livers of older KO compared to older KO without liver tumors." (PMID 24198826, 2013).
neurodegenerative disease (5 papers, 2020 to 2024). A disorder of the central nervous system characterized by gradual and progressive loss of neural tissue and neurologic function. "The deubiquitinase YOD1 was proposed to contribute in the pathogenicity of neurodegenerative diseases by reducing ubiquitination of abnormal proteins and their degradation." (PMID 34956196, 2021). "Overall, such data suggest that the deubiquitinase YOD1 contributes to the pathogenesis of neurodegenerative disease by affecting the ubiquitin–proteasome system and autophagy–lysosome pathway." (PMID 33343629, 2020). "A few studies have highlighted the significant role of YOD1 in neurodegenerative disease." (PMID 33343629, 2020).
infection (3 papers, 2014 to 2025). The state of being infected such as from the introduction of a foreign agent such as serum, vaccine, antigenic substance or organism. "Gene set enrichment analysis indicated that YOD1 plays a significant role in severe infection, macroautophagy, and immune-related mechanisms." (PMID 40867920, 2025). "We constructed YOD1 over-expression and YOD1 knockdown lentiviruses using GFP as a separate marker for infection efficiency." (PMID 37454155, 2023). "On the contrary, transfection of miR-21 mimics, knocking down of YOD1 or infection of CVB3 induced more cytoplasmic distribution of desmin than the controls." (PMID 24722419, 2014).
YOD1 also shares sentences with these, for which no sentence is quoted: osteosarcoma (3 papers); Parkinson disease (3); colon cancer (2); acute myeloid leukemia (1); Alzheimer disease (1); bipolar disorder (1); brain diseases (1); clear cell renal carcinoma (1); diabetes (1); Disseminated intravascular coagulation (1); gastric tumors (1); heart disease (1); Hypertension (1); hypertrophic cardiomyopathy (1); Myocardial fibrosis (1); myocardial infarction (1); myocardial ischemia (1); myocarditis (1); pancreatic adenocarcinoma (1); Parkinson’s (1); rhabdomyosarcoma (1); Spinocerebellar ataxia type 3 (1); Wolfram syndrome (1).